SQSTM1 (sequestosome 1)
Diseases named in the same sentence as SQSTM1 in open-access papers (continued):
Sharing a sentence is not in itself a finding about the gene and the disease.
Paget’s disease of bone (29 papers, 2012 to 2025). "The association between autosomal dominant SQSTM1 mutations and Paget’s Disease of Bone is well-established and consistent with this identified enrichment." (PMID 39825393, 2025). "Some SQSTM1 variants are also linked to Paget's disease of bone (PDB), indicating potential interactions with other genetic or environmental factors influencing ALS risk or disease phenotype." (PMID 40170896, 2025). "UKB participants with variants in SQSTM1 were enriched for “Paget’s Disease of Bone”, a disorder characterized by joint stiffness, weakness, and abnormal bone growth resulting from new bone failing to effectively replace old bone." (PMID 39825393, 2025). "Further genetic testing revealed mutations in SQSTM1 previously associated with Paget's disease of bone." (PMID 39501809, 2024). "Sqstm1 also known as p62 whose gain of function mutations were linked to Paget’s disease of bone with disruption of bone renewal cycle causing weakening and deformity." (PMID 36752600, 2023). "We identified two families with Paget's disease of bone (PDB) linked to the p.Pro392Leu mutation within the SQSTM1 gene displaying a possible digenism." (PMID 35241069, 2022). "The ubiquitin-associated domain of SQSTM1/p62 is frequently mutated in patients with Paget’s disease of bone." (PMID 34735553, 2021). "Mutations in Sequestosome-1 (SQSTM1) was initially discovered in patients with Paget’s disease of bone and linked to ALS and behavioral FTD in 2011." (PMID 32116499, 2020). "Paget’s bone disease, the second most frequent metabolic bone disorder after osteoporosis, is also affected in the same autophagy pathway by functional impairment of SQSTM1/p62 as a consequence of SQSTM1 gene mutations and proteasomal pathway impairment." (PMID 25690002, 2015). "The importance of adequately functioning autophagy for normal osteoclast differentiation is apparent in Paget’s Disease of Bone, where mutations in the ubiquitin binding protein p62/SQSTM1 results in aberrant osteoclastogenesis." (PMID 26215816, 2015). "Although mutations in SQSTM1 have originally been identified in patients with Paget disease of bone (PDB), a recent study has revealed several missense variants in SQSTM1 in familial as well as sporadic ALS." (PMID 22852081, 2012). "Mutations of the SQSTM1 gene have been detected in a high proportion of patients with Paget's disease of bone (PDB), thus highlighting the critical importance of p62 in the regulation of bone physiology." (PMID 22216904, 2012). "Variants of the SQSTM1 gene were originally reported in Paget’s disease of bone." (PMID 31475037, 2019). "Mutations in the ubiquitin associated (UBA) domain of SQSTM1/p62 have been reported to be associated with about 30% of Paget’s bone disease, which has disordered NF-κB-dependent osteoclast function and is characterized by focally increased and disorganized bone remodeling." (PMID 23110561, 2012). "Sequestosome 1 (SQSTM1) gene encodes the sequestosome 1/p62 protein, with suspected roles in FTD, Paget bone disease, or familial and sporadic forms of ALS." (PMID 37566027, 2023). "SQSTM1/p62 gene, which is mutated in some cases of ALS, Paget’s bone disease, and frontotemporal dementia, encodes a protein that plays a crucial role in autophagy." (PMID 25690002, 2015). "In a separate group of 50 patients with Paget's disease of bone with the same SQSTM1 mutations, the TIA1 polymorphism was not present." (PMID 39501809, 2024). "Paget’s disease of bone (PDB) is a chronic bone disorder and although genetic factors appear to play an important role in its pathogenesis, to date PDB causing mutations were identified only in the Sequestosome 1 (SQSTM1) gene at the PDB3 locus." (PMID 29782529, 2018). "Mutations in the SQSTM1/p62 gene have been reported in Paget’s disease of bone (PDB), but they are not sufficient to induce the pagetic osteoclast (OC) phenotype." (PMID 25115182, 2014).
Paget’s disease of bone (continued). "Interestingly, the sequestosome 1 gene (SQSTM1) encoding the p62 protein harbors mutations leading to ALS and Paget disease of bone (PDB)." (PMID 22890575, 2012).
gastric cancer (27 papers, 2016 to 2025). A primary or metastatic malignant neoplasm involving the stomach. "p62/SQSTM1 expression was found to be associated with Lauren histological type and lymphocyte infiltration in patients with gastric cancer." (PMID 30925913, 2019). "However, overexpression of SQSTM1 in gastric cancer tissue is associated with poor overall survival." (PMID 34484469, 2021). "Higher SQSTM1 expression is associated with a poor prognosis in gastric cancer." (PMID 30477228, 2018). "Moreover, the increased expression of p62/SQSTM1 is found to be associated with poor differentiation and reduced lymph node metastasis of gastric cancer." (PMID 26910278, 2016). "Recent evidence has also implicated RNautophagy in the development of chemoresistance to decitabine in gastric cancer, where SQSTM1-mediated degradation of Linc00942 leads to elevated DNA methylation levels via increased DNMT3A expression." (PMID 39164641, 2024). "Studies have reported that autophagy in gastric cancer regulates the expression of PD-L1 through the P62/SQSTM1-/NF-κB signaling pathway." (PMID 37006252, 2023). "LDHA, an enzyme controlling lactate production and the Warburg effect, is highy succinylated at K222 in gastric cancers that prevents K63-ubiquitinated LDHA from interacting with sequestosome 1 (SQSTM1) and thus reduces its lysosomal degradation." (PMID 36605449, 2022). "Meanwhile, another study demonstrated that autophagy regulates PD-L1 expression in gastric cancer through the p62/SQSTM1-NF-κB pathway." (PMID 36544757, 2022). "We discovered that autophagy regulates PD-L1 expression in gastric cancer through the p62/SQSTM1-NF-κB pathway." (PMID 30925913, 2019). "In AGS gastric cancer cells, the flavonoid kaempferol induced autophagy (accumulation of LC3B-II, BECLIN-1, and ATG5 and decreased levels of SQSTM1/P62) and autophagy-related cell death linked to the decrease in G9a content and the stabilization of IRE1." (PMID 31861179, 2019). "We further evaluated the clinicopathological and prognostic significance of autophagy markers, namely LC3B and p62/SQSTM1, in relation to PD-L1 in patients with gastric cancer." (PMID 30925913, 2019). "The expressions of both p62/SQSTM1 and ubiquitin are very weak in normal gastric tissue samples, while increased nuclear and cytoplasmic expression of both proteins are detected in gastric cancers." (PMID 26910278, 2016). "Indeed, a study found that pharmacological inhibition of autophagy increases the expression of PD-L1 in gastric cancer through the p62/SQSTM1-NF-κB pathway." (PMID 37834467, 2023). "Similarly, autophagy inhibition can upregulate PD-L1 expression by accumulating p62/SQSTM1 and activating NF-κB in gastric cancer." (PMID 36230955, 2022). "Autophagy regulates PD-L1 expression in gastric cancer through the p62/SQSTM1-NF-κB pathway." (PMID 34681840, 2021). "Autophagy-defective tumor cells preferentially accumulate SQSTM1, and higher expressions of SQSTM1 have been detected in several cancers including prostate, breast, kidney, liver, lung, breast, oral, colon, ovarian, head and neck and gastric cancers." (PMID 34829743, 2021). "In addition, some of the autophagy-related proteins, such as Beclin 1, microtubule-associated protein 1 light chain 3 (MAP1-LC3), and p62/sequestosome 1 (SQSTM1) have certain prognostic values for gastric cancer." (PMID 26910278, 2016). "As an example, tigecycline has been used against gastric cancer and multiple myeloma preclinical models and induced cellular autophagy through the conversion of microtubule-associated protein light chain 3-I (LC3I) to LC3II and the fragmentation of autophagic substrate sequestrosome-1 (SQSTM1)/p62." (PMID 39796688, 2024). "In gastric cancer (GC), CPT1A-mediated LDHA-K222succ reduces its binding to SQSTM1 and inhibits the degradation of LDHA, as well as promotes GC invasion and proliferation." (PMID 38882606, 2024).
gastric cancer (continued). "In gastric cancer, Tspan9 knockdown was followed by a significant decrease in the LC3-II/I ratio and a significant increase in SQSTM1/p62 levels." (PMID 38649381, 2024). "In the present study, gastric cancer cells showed increased expression of genes involved in the autophagy process, such as ATG5 and SQSTM1, after exposure to NSC305787." (PMID 38972247, 2024). "Recent studies have shown that gastric cancer-driven autocrine CCL2 activates PI3K/Akt/mTOR signaling to suppress proapoptotic autophagy, subsequently promoting sequestosome 1 (SQSTM1)-mediated CCL2 expression via NF-κB signaling." (PMID 33406733, 2021). "In gastric cancer, the expression pattern of Beclin1, LC3, and P62/SQSTM1, which are autophagy-related genes, predicts the prognosis of the tumor." (PMID 34484469, 2021). "Previous studies have also indicated that SQSTM1 can modulate autophagy for tumorigenesis and prognosis in OSCC and gastric cancer." (PMID 34830108, 2021).
Paget disease (23 papers, 2006 to 2024). A malignant neoplasm composed of large cells with large nuclei, prominent nucleoli, and abundant pale cytoplasm (Paget cells). "Over 21 mutations in human SQSTM1/p62 (a scaffold protein with a key role in autophagy) are linked to familial Paget’s disease (about 30% of all Paget’s disease cases), with p62P392L the most frequent [10•, 11, 12]." (PMID 38457001, 2024). "The colonial settlers included a small proportion carrying, and passing on, SQSTM1 mutations, but this alone cannot explain the relatively high prevalence of Paget’s disease in the settler communities observed in 1970s surveys." (PMID 38902530, 2024). "SQSTM1 mutations affecting the UBA domain of SQSTM1/p62 are frequently reported in patients with Paget’s disease of bone and we have shown that SQSTM1/p62 mutant proteins are not able to inhibit NF-κB to the same extent as wild type SQSTM1/p62." (PMID 34735553, 2021). "The most impressive animal model of Paget’s disease has been generated in transgenic mice by targeting the measles virus nucleocapsid protein and a mutated sequestosome 1 gene into the animals." (PMID 27600564, 2017). "Mutations in the gene-producing sequestosome 1 increase susceptibility to the development of Paget’s disease, but there is incomplete penetrance of the disease in some family members who have been found to harbor gene mutations." (PMID 27600564, 2017). "Sequestosome1 (SQSTM1) is the only gene currently identified and associated with Paget’s disease of the bone." (PMID 23036272, 2012). "Mutations have now been identified in four genes that predispose to PDB and related diseases (reviewed by Daroszewska & Ralston) but the most important of these is SQSTM1 which is a common cause of classical Paget's disease." (PMID 18510762, 2008). "By answering these research questions, this study will cast light on the feasibility of developing a programme of genetic testing and preventive treatment for individuals who are at high risk of developing Paget's disease because they carry SQSTM1 mutations." (PMID 18510762, 2008). "In view of this, it is timely to investigate the clinical potential for a programme of genetic testing and preventive treatment for patients who carry SQSTM1 mutations, in an effort to prevent or delay the development of Paget's disease." (PMID 18510762, 2008). "In view of this, it is timely to investigate the clinical potential for a programme of genetic testing and preventative treatment for patients who carry SQSTM1 mutations, in an effort to prevent or delay the development of Paget's disease or its complications." (PMID 16762063, 2006). "By answering these research questions, this study will cast light on the feasibility of developing a programme of genetic testing and preventative treatment for individuals who carry SQSTM1 mutations that are at high risk of developing Paget's disease." (PMID 16762063, 2006). "P62/SQSTM1 may also be involved in bone diseases, as a high frequency of SQSTM1 gene mutations were reportedly observed in patients with Paget’s disease." (PMID 37856460, 2023). "Furthermore, mutations of p62/SQSTM1 have been linked to Paget’s disease too, a disorder of bone metabolism." (PMID 34830777, 2021). "The Zoledronate in the Prevention of Paget’s disease trial (ZiPP) will determine if prophylactic therapy with the bisphosphonate zoledronic acid (ZA) can delay or prevent the development of PDB in people who carry SQSTM1 mutations." (PMID 31488492, 2019). "This raises the possibility that patients who carry SQSTM1 mutations and who are at high risk of developing Paget's disease could be offered prophylactic therapy, in an attempt to prevent the disease occurring, or to prevent complications developing." (PMID 16762063, 2006). "miR27a participates in osteoclast differentiation through the mediation of sequestosome 1 (Sqstm1/p62), which has been implicated in RANK-mediated osteoclastogenesis in Paget’s disease." (PMID 39452495, 2024).
Paget disease (continued). "Two genes involved in bone formation, SQSTM1 and TNFRSF11A, have been shown to cause Paget's disease." (PMID 21619704, 2011). "On case note review, neither patient with the hnRNPA2B1 variant or the SQSTM1 variant had evidence of multisystem disease typical of the genes (inclusion body myopathy or Paget’s disease)." (PMID 36515702, 2023). "In patients affected by Paget’s disease with mutations of SQSTM1, defective p62 does not allow the CYLD protein to bind to the TRAF6 complex by causing osteoclast differentiation and activation." (PMID 33008140, 2020). "Genetic factors have long been recognised to play an important role in Paget's disease and recent studies by our own group and others indicate that between 40–50% of instances of familial Paget's disease are caused by mutations affecting the ubiquitin-associated (UBA) domain of the SQSTM1 gene." (PMID 16762063, 2006). "Similarly, genes such as TANK-binding kinase-1 (TBK1), Sequestosome-1 or p62 (SQTSM1), Optineurine protein (OPTN), and Valosin-containing protein (VCP) that are associated with FTD, inclusion body myositis, motor neuron disease, and Paget's disease encode proteins related to protein degradation." (PMID 35115992, 2021).
lung cancer (19 papers, 2012 to 2025). A malignant neoplasm involving the lung. "It has been reported that there is an association between p62/SQSTM1 staining and clinical survival in lung cancers." (PMID 24086340, 2013). "Our data also showed that PRKCSH depletion promoted the degradation of the autolysosomal substrate SQSTM1 protein in lung cancer cells, and its level was increased via the lysosome inhibitor CQ." (PMID 38200153, 2024). "Expression of p62/SQSTMQ1 is shown to promote tumorigenesis and augmented levels of p62/SQSTM1 are frequently found in various human cancers including pancreas, prostate, liver and lung cancers." (PMID 33802014, 2021). "p62/SQSTM1 deficiency in cancer cells significantly impedes cancer cell growth and inhibition of p62/SQSTM1 suppresses KRAS-driven lung cancers in a genetically engineered mouse model." (PMID 33802014, 2021). "HACE1 is also reported to ubiquitylate the autophagy receptor Optineurin (OPTN), which in turn facilitates OPTN interactions with p62/SQSTM1 to activate autophagy to inhibit growth and tumorigenicity of lung cancer cells." (PMID 30622235, 2019). "The protein expression of p62 (also called sequestosome-1) and Atg5 (autophagy protein 5) was found in 44 out of 118 (37.3%) and 70 out of 131 (53.4%) patients with primary lung cancer, respectively." (PMID 29545906, 2018). "Furthermore, multiple studies reported that SQSTM1 could serve as a novel prognostic biomarker in multiple cancers types, including nasopharyngeal carcinoma, lung cancer, oral squamous cell carcinoma, and HCC." (PMID 32807131, 2020). "MEN1-KD also inhibited the mRNA levels of ATG5, SQSTM1, and MAP1LC3B and decreased the protein levels of P62 and LC3B-II in another lung cancer cells (p < 0.05)." (PMID 40057469, 2025). "In a model of lung cancer, knockdown of ATG5, BECN1, ATG7 and p62/SQSTM1 decreases A549 cell invasiveness in the presence of cancer-associated fibroblasts (CAFs)." (PMID 37887330, 2023). "Altogether, LAI-1 potently blocked autophagy at concentrations higher than 15 μM, as it significantly increased LC3-II/I and p62/SQSTM1 levels in all lung cancer cell lines, without relevant differences." (PMID 35884450, 2022). "In addition to ECH, SQSTM1-ALK has also been reported in some cases of ALK-positive large B-cell lymphoma and lung cancer." (PMID 29747676, 2018).